LINC00433 (long independently transcribed non-coding RNA 433)
Synonyms: LINC00560
Gene: Long non-coding RNA gene on chromosome 13 (88,494,789 to 88,630,397, forward strand). Ensembl gene ENSG00000229443.
Diseases named in the same sentence as LINC00433 in open-access papers:
LINC00433 is named in the same sentence as 1 disease in open-access papers, as found by Europe PMC text mining. Sharing a sentence is not in itself a finding about the gene and the disease. The quoted sentences say what the papers report.
neurodegenerative disease (1 paper, 2020). A disorder of the central nervous system characterized by gradual and progressive loss of neural tissue and neurologic function. "These include a locus on chromosome 4q24, which encompasses TET2, a gene encoding a DNA demethylase with known roles in the microglial inflammatory response and neurodegenerative diseases;77,78 and a locus on chromosome 13q31.2, which encompasses LINC00433 but no protein-coding gene." (PMID 32699239, 2020).